KEAP1 (kelch like ECH associated protein 1)
Diseases named in the same sentence as KEAP1 in open-access papers (continued):
Sharing a sentence is not in itself a finding about the gene and the disease.
tumor (continued). "We explored a cohort of 186 sequentially profiled HNSCC patients for tumor-specific somatic mutation in Keap1 only (n = 1), Nrf2 only (n = 7), or both (n = 1)." (PMID 35945195, 2022). "The excellent anti-tumor effect shows that ISP-I provide a new therapeutic option targeting to NSCLC patients carrying KEAP1 mutation through excessive ROS accumulation and play dual roles as a PI3K/AKT pathway inhibitor simultaneously." (PMID 35813464, 2022). "Patient L2 TB and CDX presented a KRAS-mutant tumor with concurring mutations in genes KEAP1, STK11, and RBM10." (PMID 35511434, 2022). "One clinical trial is also screening for tumor mutations in KEAP1 or NRF2/NFE2L2 genes (NCT04698681)." (PMID 35204312, 2022). "One well-documented mode of adaptation involves increased production of antioxidants often associated with inactivation of the KEAP1 tumour suppressor gene and the resulting upregulation of the NRF2 transcription factor." (PMID 36176767, 2022). "Nrf2 overexpression can cause chemical-sensitive tumor cells to resist ferroptosis inducers by inhibiting KEAP1 overexpression." (PMID 36059675, 2022). "Keap1-mutated tumors are dependent on glutaminolysis and activate the pentose phosphate pathway, the inhibition of which abrogated tumor growth." (PMID 35406531, 2022). "Series of co-occurring mutations in these genes (KRAS, LKB1, and KEAP1) associated with NRF2 overexpression drive tumor progression by causing and supporting metabolic shift and reprogramming resulting in metastases and cis-platinum resistance." (PMID 35268568, 2022). "There is also evidence that tumor growth is associated with somatic mutation in the Keap1-Nrf2 system, disrupting the interaction between Nrf2 and Keap1, which finally leads to constitutive stabilization and activation of Nrf2." (PMID 34073079, 2021). "Some studies have suggested that the irreplaceable role of the Kelch-like ECH-associated protein 1 (KEAP1)/nuclear factor E2-related factor 2 (Nrf2) pathway in tumor metabolism." (PMID 34113573, 2021). "Taken together, these findings indicated that KEAP1 mutation is likely associated with impaired presenting processes of tumor specific neoepitopes, therefore impairing tumor immunity." (PMID 34328274, 2021). "With the data collected from The Cancer Genome Atlas (TCGA), we evaluated the association of KEAP1 mutation with tumor infiltrating leukocytes (TILs), including dendritic cell, CD8 T cell, CD4 T cell, neutrophil, B cells, and macrophage." (PMID 34328274, 2021). "Mutations in either KEAP1 or NFE2L2 were found only in KRAS-driven tumor in our cohort and were associated with upregulation of all 3 AKR genes." (PMID 34344431, 2021). "In this study, we have performed a comprehensive investigation of KEAP1 gene mutation in LUAD patients with focus on its associations with immune microenvironment of tumor." (PMID 34328274, 2021). "On the one hand, Keap1 plays a role similar to that of oncogenes, and on the other hand, Keap1 abnormalities promote the biological malignant effects of tumor cells and are associated with poor prognosis in solid tumors." (PMID 34466284, 2021). "A second mechanism promoting tumor cell survival in hypoxic conditions is the nuclear factor (erythroid-derived 2)-like 2-kelch-like ECH-associated protein 1 (Keap1-Nrf2) pathway." (PMID 34316328, 2021). "In vivo studies in K-RAS-driven human LUAD xenografts and PDXs exhibiting KEAP1 mutations show a reduction in tumor growth after treatment with glutaminase inhibitor CB-839." (PMID 34440648, 2021).
tumor (continued). "The KEAP1-Nrf2 pathway is considered an important player in tumor progression, where expression of Nrf2-associated antioxidant genes confers protection to the tumor from environmental stress that contributes to chemoresistance and radioresistance." (PMID 34298809, 2021). "We assessed the association between KEAP1 mutation and tumor microenvironment in LUAD systematically." (PMID 34328274, 2021). "Further experiments revealed that LONP1 negatively regulates the nuclear factor E2-related factor 2/Kelch-like ECH-associated protein 1 (Nrf2/Keap1) signalling pathway to affect tumour growth." (PMID 34503532, 2021). "The positive correlation between pNrf2 and Keap1 and the association between Keap1 and increased proliferative activity in this study were unexpected, as Keap1 is known to suppress Nrf2 activation and, thus, expected to have tumor-suppressive effects." (PMID 32751896, 2020). "As an oxidative stress system, the Nrf2-Keap1 (Kelch-like ECH-associated protein 1) while protecting normal cells presents a paradox regarding tumor cells." (PMID 32443630, 2020). "As expected, the reduced number of colonies and migration in cells knockouted with NRF2.These data suggest that the newly found somatic mutations in KEAP1 promote tumor cell activity through activating NRF2 antioxidant stress signaling pathways." (PMID 32576270, 2020). "When pathway analysis was carried out, alterations in those linked to oxidative stress were found in 22% of tumours due to mutations in KEAP1 (mutated in 19%), CUL3 (mutated in >1%) and NFE2L2 (mutated in 3%)." (PMID 33276631, 2020). "The most obvious way of treating tumours harbouring mutations in NFE2L2 or KEAP1 is with drugs that inhibit NRF2 activity, and a range of small molecules have been reported to possess this ability." (PMID 33276631, 2020). "The 11 CpG sites and their corresponding 9 genes showed significant differential methylation and gene expression between KEAP1-mutated and wild-type tumor samples." (PMID 32327612, 2020). "In HCC cells, mutations in NFE2L2 or KEAP1 activate the Keap1/Nrf2 pathway, increasing the nuclear abundance of Nrf2 and promoting the subsequent activation of its target genes, which results in tumor cell survival and promotion of tumorigenesis." (PMID 33066023, 2020). "This has been highlighted by the findings that KRAS mutant tumours with co-occurring KEAP1 mutations are associated with later stage lung cancer." (PMID 33276631, 2020). "A total of 137 differentially-methylated CpG sites were found between KEAP1-mutated and wild-type tumor samples after Benjamini Hochberg-false discovery rate (BH-FDR) adjustment (delta β > |0.2|, P <0.05)." (PMID 32327612, 2020). "In order to investigate the effect of changes in DNA methylation associated with KEAP1 mutations on gene expression, we subjected the discovery data set (30 KEAP1-mutated versus 155 wild-type tumor samples) to DEG analysis." (PMID 32327612, 2020). "Dietary changes are also reflected in TIF nutrient levels, while introduction of a Keap1 mutation into LUAD cells had a smaller effect on the composition of the metabolic tumor microenvironment." (PMID 30990168, 2019). "In some tumors, Nrf2 is determinedly stimulated because of somatic mutations in either Nrf2 or Keap1, and, therefore, upholding tumor development and resistance to oxidants and anticancer drugs." (PMID 31022969, 2019). "Keap1 loss activates the pentose phosphate pathway, inhibition of which, using 6-AN, abrogated tumor growth." (PMID 31519898, 2019).
tumor (continued). "Recently, NRF2/KEAP1 mutation or deficiency has been reported to increase tumor metastasis, resistance to oxidative stress in tumor cells, and recurrence in patients undergoing radiotherapy for lung SCC." (PMID 31319622, 2019). "The loss of inhibition by Keap1, caused by somatic mutations or epigenetic changes, results in increased Nrf2 stability in different types of human tumor." (PMID 31811110, 2019). "Somatic mutations of the LUSC2 tumor were also found in a number of novel driver genes such as Myh9, Kmt2d and Keap1." (PMID 29484121, 2018). "In tumor cells harboring mutant FH, an accumulation of fumarate results in succination of cysteine-modifying proteins such as kelch-like ECH-associated protein 1 (KEAP1) and mitochondrial aconitase (ACO2)." (PMID 28748451, 2018). "NRF1/2 protein turn-over in tumor cells is controlled by the kelck-like EZH-associated protein 1 (KEAP1) and other ubiquitin ligase complexes." (PMID 29487387, 2018). "Consistent with the literature, certain tumor subtypes show higher representation of either somatic NRF2 or KEAP1 mutations." (PMID 30150714, 2018). "The nuclear factor erythroid 2-related factor 2 (Nrf2)/Kelch-like ECH-associated protein 1 (Keap1) signaling pathway is one of the crucial defense systems against oxidative stress in tumor tissues and cells." (PMID 30619751, 2018). "NRFs are regulated by Kelch-like ECH-associated protein 1 (KEAP1) and are well-known for their cellular antioxidant defense role in neuron protection, liver protection and tumor suppression." (PMID 28881853, 2017). "In A549 cells, an inactivating mutation within the KEAP1 tumor suppressor gene reduces the affinity of KEAP1 for the NRF2 transcription factor, leading to greater accumulation of NRF2 in the nucleus and increased activation of genes coding for antioxidants." (PMID 28147323, 2017). "NRF2 positivity and Keap1 negativity were frequently associated with more advanced tumors (i.e., higher histological grade, lymph node involvement, and higher tumor stages) (p<0.05 for all)." (PMID 26247201, 2015). "Our findings differ from those of previous publications that Keap1 and nuclear Nrf2 were associated with more advanced tumor stage." (PMID 24386210, 2013). "Three tumour samples presented mutations in NFE2L2 (gene encoding for NRF2) or KEAP1." (PMID 39707614, 2025). "The characterization of the tumour immune microenvironment of KEAP1-mutant tumours in a K1P mouse model showed impaired expansion of CD11c+ immune cells, further emphasizing the immunosuppressive effects of KEAP1 mutations." (PMID 40647497, 2025). "However, in certain tumours this pathway is constitutively activated due to gain-of-function mutations in NFE2L2 (encoding NRF2) or loss-of-function alterations in KEAP1 or CUL3, promoting cell proliferation and drug resistance." (PMID 40849356, 2025). "STK11 (LKB1) loss and KEAP1 loss both confer a more aggressive, therapy-resistant tumor biology." (PMID 40723270, 2025). "Moreover, a smaller number of driver mutations and deletions in tumor suppressor genes (for example, KEAP1 and SMAD4) were also significantly associated with high clone proliferation, matching results in previous cell line small interfering RNA experiments." (PMID 39614124, 2025). "In tumors harboring initiating MAPK driver alterations, activation of the NRF2 pathway via heterozygous KEAP1 mutation may act as a cooperative event, enhancing tumor progression." (PMID 41573641, 2025). "Since NRF2 influences both innate and adaptive immunity, KEAP1 mutations may also play a significant role in modulating the tumour microenvironment." (PMID 40647497, 2025).
tumor (continued). "In LUAD, STK11 and KEAP1 mutations have been implicated in promoting aggressive tumor behavior." (PMID 40427178, 2025). "Dysregulatin on RSPO3 (a R‐spondins ligand of LGR4)‐LGR4 signaling in LUAD with Keap1 deficiency could facilitate tumor aggressiveness." (PMID 40364562, 2025). "The response in patients with KEAP1-mutated tumours has also been studied based on clonality." (PMID 40647497, 2025). "Moreover, our finding that KEAP1 mutations not only drive tumor growth and migration but also attenuate cellular response to selpercatinib in RET fusion-positive cells highlights their clinical significance." (PMID 41573641, 2025). "The higher frequency of KEAP1/STK11 co-mutations in patient-derived cell lines compared with tumor datasets suggests a potential selective advantage for in vitro establishment, possibly because of enhanced glutamine utilization and reactive oxidative stress resistance." (PMID 40427178, 2025). "However, the mechanism by which KEAP1 or STK11 mutations impeding tumor immunogenicity and immunotherapeutic response remains elusive." (PMID 41378285, 2025). "NRF2 and its negative regulator Kelch-like ECH-associated protein 1 (KEAP1) have been the focus of numerous investigations in elucidating whether NRF2 suppresses tumor promotion or conversely exerts pro-oncogenic effects." (PMID 38247494, 2024). "It is suggested that neutrophils, rather than other immune cells, may play a crucial role in the tumour immune microenvironment of LUAD patients with KEAP1 mutation." (PMID 38962454, 2024). "Notably, mutations in Keap1 are linked to a higher tumor mutational burden and elevated PD-L1 levels, which are often associated with better outcomes following checkpoint inhibitor treatments." (PMID 39286246, 2024). "Looking at a possible correlation between methylation, mutations, and loss of heterozygosity (LOH) in the KEAP1 gene and the disease course, it was observed that the degree of KEAP1 inhibition showed a trend of association with a higher risk of tumor progression." (PMID 39050569, 2024). "Notably, the relationship between KEAP1 mutations and a low number of tumor-infiltrating lymphocytes suggests a link between Nrf2 hyperactivity and immune evasion." (PMID 39769005, 2024). "KEAP1 mutation significantly suppresses the tumour immune microenvironment in LUAD patients." (PMID 38962454, 2024). "Indeed, this study suggested that KEAP1 functions as a tumor suppressor in RCC, with decreased expression linked to poor prognosis and reduced sensitivity to axitinib." (PMID 39769005, 2024). "KEAP1 mutation can affect the tumor immune microenvironment and cause immune escape." (PMID 38884095, 2024). "To address this, we explored the hypothesis that Keap1/Nrf2 mutations in head and neck stem and progenitor cells were linked to frequent lung metastasis, aggressive tumor behavior, and failure of chemoradiation, and in some cases, targeted therapy." (PMID 37894373, 2023). "In the current study, we investigated whether tumour-intrinsic KEAP1/NRF2 mutations could be non-invasively imaged by [18F]FSPG PET imaging and whether aberrant system xc− expression could be exploited for treatment of refractive NSCLC tumours." (PMID 38168428, 2023). "The existence of Keap1/Nrf2 mutations in HN-CSCs, as well as their correlations with tumor mutations, pathologic tumor stage, tumor histologic grades, lung metastasis, treatment outcomes, and the patient’s age and conditions, are assessed at the last follow-up visit." (PMID 37894373, 2023). "Numerous DPP III mutations have been found in human tumor genomes, and it is suggested that some of them may alter affinity for KEAP1." (PMID 35216111, 2022).
tumor (continued). "It would be interesting to investigate whether loss of Keap1 and overexpression of Nrf2 status in tumor samples are clinically relevant mechanisms of chemotherapeutic resistance in HNSCC and develop alternative therapy to counter Nrf2 activation." (PMID 35945195, 2022). "Moreover, the KEAP1/NRF2 mutation status of patients with NSCLC can affect local recurrence after radiotherapy through tumor invasion and metastasis." (PMID 36360316, 2022). "KEAP1 mutation has a dramatic effect on the tumor immune microenvironment of LUAD and may also serve as a predictive biomarker for immunotherapy." (PMID 35178154, 2022). "Moreover, FSP1 suppressed the level of 4-HNE (a by-product during lipid peroxidation) in these tumors, suggesting FSP1-mediated ferroptosis resistance contributes to tumor growth of KEAP1-deficient cells." (PMID 36264074, 2022). "Furthermore, NGS of the tumor tissue of the same patients identified tumor-specific pathogenic or likely pathogenic mutations in Kelch-like ECH-associated protein 1 (KEAP1), neurogenic locus notch homolog protein 1 (NOTCH1), and KRAS only in responders." (PMID 36844924, 2022). "However, somatic mutations of NRF2 and KEAP1 only occurred in small portion of tumor samples and varied from different clinicopathologic characteristics." (PMID 35754474, 2022). "Tumor cells with Keap1 mutations (SSC9 and Keap1-mutated patient’s tumor cells) demonstrated increased nuclear localization of Nrf2 in comparison to normal and Keap1 wild-type (Cal33 and Keap1 wild-type patients’ tumor cells) cells." (PMID 35945195, 2022). "In general, the genomic changes of these two subtypes are mainly mediated by gene mutations, especially KEAP1, which may contribute to the heterogeneous response of subtypes to tumor treatment, leading to different clinical outcomes." (PMID 36238302, 2022). "It is clear that tumour cells display peculiar features such as excessive stress due to ROS imbalance and this may cause Nrf2 hyperactivation or Keap1 downregulation, thereby shifting the balance toward antioxidant and pro-survival response." (PMID 34360732, 2021). "Further, the results revealed that the association among the Nestin–Keap1–Nrf2 pathway, tumor phenotypes, and antioxidant defenses could be regarded as a possible treatment target for GC." (PMID 34772403, 2021). "KEAP1 mutation has a significant effect on the tumor immune milieu of LUAD and may play as a predictive biomarker of immunotherapy for LUAD patients." (PMID 34328274, 2021). "Taken together, all of these results confirmed at the level of pathway that KEAP1 mutation could possibly have defective impact on tumor immunity." (PMID 34328274, 2021). "The presence of co-mutations such as STK11 or KEAP1 shape the tumor immune microenvironment and might has an impact on treatment efficacy." (PMID 35096591, 2021). "However, we now have evidence that constitutive NRF2 activation via mutations in KEAP1 or recurrent NFE2L2 exon 2 deletions can drive tumor proliferation and metastasis." (PMID 33769711, 2021). "Animal experiments further indicated that Keap1 R320Q somatic mutation could accelerate tumor growth in nude mouse." (PMID 34466284, 2021). "The progression‐free survival (PFS) analysis, which can better reflect tumor progression and predict clinical benefits, also showed an association between KEAP1/NFE2L2/CUL3 mutation and faster disease progression (median survival time: 17.7 months vs. 31.7 months, p = 0.016)." (PMID 34617407, 2021). "Finally, a pooled analysis from OAK and POPLAR studies showed that among patients receiving atezolizumab in second or third-line settings, those with STK11/KEAP1 tumor mutation had worse median OS compared with WT patients (7.3 vs. 15.6 months (p = 0.004))." (PMID 34831355, 2021). "It is, therefore, assumable that KEAP1 mutated LUADs could possibly have lower tumor immunity, compared to the wild type patients." (PMID 34328274, 2021).